IL10 (interleukin 10)
Diseases named in the same sentence as IL10 in open-access papers (continued):
Sharing a sentence is not in itself a finding about the gene and the disease.
parasitemia (continued). "The blockade of IL-10 signaling resulted in increased inflammatory cytokine production and death of the animals despite reduced levels of parasitemia." (PMID 40972121, 2025). "Blocking IL-10 signaling rapidly reduced the parasitemia level (within 4 days of the first anti-IL-10R antibody injection) and plasmodial levels remained low for nearly 2 weeks." (PMID 40972121, 2025). "Untreatedmice displayed elevated parasitemia and pro-inflammatory cytokinelevels, with strain-specific differences in IL-10 levels and the presenceof parasites in the myocardium." (PMID 40488037, 2025). "Positive disease outcome during Δplp1 parasite infection is also associated with regulated induction of proinflammatory cytokines, including IFN-γ and TNF-α, and an earlier IL-10 regulatory response that is dysregulated during WT infection." (PMID 40166190, 2025). "IL-6 and IL-10 levels were positively correlated with parasitemia and with total IgG levels; but they were negatively correlated with the gestational age at delivery from Pv-infected woman." (PMID 39495782, 2024). "Polarization of M2 macrophages is stimulated by cytokines (such as IL-4, IL-10, and IL-13) and parasite infection." (PMID 39123188, 2024). "IL-10 has been shown to have anti-inflammatory properties to protect hosts from a number of parasitic diseases, such as trypanosomiasis." (PMID 38521853, 2024). "We identified Q586B2 as a T. brucei protein that induces IL-10 in myeloid cells, which promotes parasite infection invasiveness." (PMID 38413606, 2024). "brucei parasites employ Q586B2 to trigger early IL-10 production by myeloid cells at the site of infection, which promotes a higher first-peak of parasitemia." (PMID 38413606, 2024). "Mechanistically, BHLHE40 suppresses IL-10 production by co-binding to a regulatory region with c-Maf in the Il10 locus in T cells and myeloid cells, which in turn promotes proinflammatory cytokine production during intracellular parasite infections." (PMID 38271477, 2024). "There was a trend towards a decrease in temperature and the levels of the top five most upregulated cytokines during the participant’s second exposure to high parasitemia, IL-10, CXCL10, IL-1RA, IFNγ, IL-6." (PMID 38890271, 2024). "In this context, an increase in IL-10 levels often leads to the expansion of the parasitic infection population, in addition to contributing to the establishment of a chronic state of infection." (PMID 39065160, 2024). "Previous studies have reported a disturbed balance between proinflammatory IFN-γ and anti-inflammatory IL-10 in Bhlhe40-/- mice during intracellular parasite infections." (PMID 38271477, 2024). "Children with high parasite density (>10,000 parasites/μL) had higher plasma levels of TNF‐α (p < .001), IFN‐ɣ (p < .001), IL‐1β (p < .001), IL‐6 (p < .001), GM‐CSF (p < .001), and IL‐10 (p < .001) than those with low parasitemia." (PMID 39240033, 2024). "From this, we identified 26 common DEGs downregulated in Tr1 cells from both parasitic diseases, including Ccr7, Tcf7, and Bcl6, as well as 29 upregulated DEGs, including Il10, Havcr2, Prdm1, Ccr2, Ccr5, Maf, and Lag3." (PMID 37917177, 2023). "Mechanistic studies demonstrated that CD4+ T-cells (but not CD8+ T-cells), and Th1 and Th2 cytokines (interferon gamma and tumor necrosis factor, IL-10) were critical in controlling parasitemia and survival following challenge." (PMID 37962347, 2023). "The immune depression role of IL-10 during parasite diseases is already reported in the literature, although most findings are based on in vitro and in vivo studies." (PMID 37243099, 2023). "E8.5 infected mice had elevated transcripts for Ifnγ, Tnf, Il10, Cox1, Cox2, Sod1, Sod2, Cat, and Nrf2, while Sod3 was the only transcript that correlated with parasitemia." (PMID 35312688, 2022).
parasitemia (continued). "The present literature survey documents extensively the opposite activities of the polarising cytokines MIF and IL-10 during infections with various extracellular and intracellular pathogens, but with a special emphasis on parasitic disease." (PMID 35464430, 2022). "Th2 cells are critical for the control of certain parasitic infections through the production of the clustered group of cytokines IL-4, IL-10 and IL-13." (PMID 35215986, 2022). "Th1 subsets mainly express IFN-γ and IL-2, which are involved in cellular immunity to endogenous cell infection, while Th2 subsets express IL-4 and IL-10, which participate in allergic reactions and humoral immunity against parasitic infection." (PMID 36425118, 2022). "Evidence from other parasitic infections have confirmed this role of IL-10 in limiting inflammation and pathology but have also put forward that this is often accompanied with decreased pathogen clearance (in contrast to trypanosomiasis)." (PMID 35464430, 2022). "The median IL-6 level was between 3- and 4-fold lower in the case of a parasitic infection within the adult group, while an IPI was associated with a higher IL-10/IL-6 ratio." (PMID 35421083, 2022). "Second, chronic parasite infection can generate a pool of regulatory T (Treg) cells that secrete transforming growth factor TGFβ and IL-10." (PMID 36517588, 2022). "In contrast, the interruption of the PD-1/PD-L1 pathway showed an increase in parasitemia as well as in the production of regulatory cytokines such as IL-10." (PMID 35812458, 2022). "By 8 days PI, parasitemia in Mcpt4-/- mice was correlated mainly with type-2 cytokines including large fold-changes in IL-3 and IL-10, which were also notable in Mcpt4+/+ mice." (PMID 35154114, 2022). "During parasitic infection with T. cruzi, IL-10 has already been identified as a key cytokine, mediating an intimate balance between effective immunity and immunopathology." (PMID 35464430, 2022). "While some cytokines reached a maximum at peak parasitemia (IL-8, IL-10, KC-like) others rose only after the infection was treated (TNF, IL-6, MCP-1)." (PMID 34399690, 2021). "They reported that IL-10-producing NK cells migrate into the spleen and hepatic granulomas of L. donovani-infected mice and suppress host resistance to disseminated parasitosis, which is dependent on IL-10 production." (PMID 35053151, 2021). "IFN-γ and IL-10 are both essential for mice to survive acute T. gondii infection, but IFN-γ is necessary to control parasitemia and IL-10 is necessary to control the host immune response." (PMID 33526566, 2021). "A recent study showed a positive relationship between the IL-10 levels in sera of CCD patients with detectable parasitemia (PCR+)." (PMID 34458163, 2021). "For example, IL-12 can induce NK cells to produce IL-10 during inflammation and parasitic infection, and IL-21 can also enhance IL-10 production by NK cell in vitro." (PMID 33365027, 2020). "In response to in vitro TLR ligation, CD16+ DCs isolated during peak parasitemia produced increased IL-10 and IL-12." (PMID 31900030, 2020). "brucei activates a Blimp-1-dependent IL-10 regulatory pathway in T cells that acts as a critical anti-inflammatory rheostat, mandatory for host survival during the acute phase of parasitemia." (PMID 32655552, 2020). "Collectively, IL-6, IL-18, IFN-γ, and IL-10 levels rose with parasitemia, while significant increases in IL-4 were biphasic, with a second peak occurring at day 10 p.i." (PMID 32958528, 2020). "IL-10 has also been shown to be produced and act as an anti-inflammatory cytokine during parasitic infection with Plasmodium spp." (PMID 32635653, 2020). "Consistent with this antagonistic role, IL-10 levels have been positively correlated with total parasitemia during CHMI." (PMID 31900030, 2020). "IL-10 levels have been correlated with higher parasitemia in vivax malaria, whereas asymptomatic patients have lower levels of IL-1034." (PMID 33028898, 2020).
parasitemia (continued). "Th1 cells mainly secrete cytokines such as IFN-γ and IL-2, which play an important role in antiviral and bacterial immune responses, while Th2 cells mainly secrete cytokines such as IL-4 and IL-10, which play a role in parasitic infection." (PMID 33294465, 2020). "The serum adenosine deaminase (ADA) activity was therefore assessed as this can potentially influence host suppressive Th2 immune response (IL-10) during the progression of early parasitemia in asymptomatic individuals." (PMID 32555598, 2020). "The IL-10 wave follows peak pro-inflammatory cytokine production, which accompanied the control of peak parasitemia." (PMID 32655552, 2020). "Excessive il-10 is also considered a critical biomarker for poor disease outcome after infection in several parasitic diseases of mammals." (PMID 32582181, 2020). "On the other hand, IL-10, which is often assessed as a marker of Th2 response, in principle plays an important regulatory role during parasite infection." (PMID 31635267, 2019). "Although IL-10 is an important immunomodulator in viral, bacterial, and parasitic infections, only a few studies have investigated the IL-10 released by Bregs in the control of infectious diseases." (PMID 31474988, 2019). "Downregulation of IL-12, coupled with the upregulation of IL-10 with parasitic burden was observed which depicts the host protective mechanism in response to parasitemia load." (PMID 31614626, 2019). "The findings here have important implications for our understanding of IL-10 production by NK cells and thus their ability to dampen inflammatory responses during bacterial and parasite infections." (PMID 31552035, 2019). "IL-10 production can be significantly elevated in the pulmonary mucosa during the late stages of parasitic infection by Nippostrongylus brasiliensis (Nb), predominantly by CD4+ T cells that are LAG3/CD49b double positive." (PMID 30510554, 2018). "The effect attributed to IL-10 differs in other parasitic diseases such as Leishmania donovani, Trypanosoma cruzi, and Giardia duodenalis." (PMID 30406037, 2018). "Alkaloids treatment (SAT group and SAT + AT group) significantly stimulated expression of these complement activation-associated proteins and enhanced host immune response against parasite infection by increasing IL-2 and IL-10 level in serum." (PMID 29785189, 2018). "Our study helps further the definition of parasite infection generated, Th2 cytokine induced human alternative macrophage activation and defines a mechanism by which increased IL-10 production occurs in these cells after mycobacterial infection." (PMID 28658262, 2017). "Since the parasitemia of the IL-10KO and WT mice was similar during this period of time, the impact of both bpV(phen) and IL-10 on hepatic pathology was analyzed." (PMID 28710387, 2017). "IL-10 expression has also shown to inhibit IFNγ-dependent NO production by macrophages and thereby their ability to control parasitic infections." (PMID 29375545, 2017). "These IL-10 secreting Th1 CD4+ T cells have been identified in parasite infection models, with both effector and regulatory functions." (PMID 28810829, 2017). "Across viral, bacterial, and parasitic infections, the increased production of IL-10 has been shown to aid in the maturation of memory CD4+ and CD8+ T cells." (PMID 28270815, 2017). "During parasitic infection ablation of IL-10R expression specifically in DCs resulted in enhanced immune responses associated with elevated Th1 responses and reduced parasitemia, comparable to ubiquitous IL-10-deficient mice, demonstrating that IL-10 might act in a paracrine and autocrine manner." (PMID 28293237, 2017). "In contrast, IL-10 levels were within normal range in women infected with the parasitic disease filariasis." (PMID 29255607, 2017).
parasitemia (continued). "As parasitemia worsened from days 0 to 7, the concentrations of IL-12p70, IL-10, and IL-4 in the supernatant increased in the BMSA vaccinated group, although the concentrations of IL-2, IFN-γ, and IL-17 decreased." (PMID 29312230, 2017). "IFNγ is needed to activate phagocytosis and control parasitemia, while IL10 is crucial for counterbalancing the inflammatory response." (PMID 27802341, 2016). "Our results significantly increase our understanding of the dynamics and maintenance of IL-10 production by CD4+ T cells postinfection and reveal the functions of IL-10 during secondary parasite infections." (PMID 27630165, 2016). "The aim of this study was to investigate L. infantum-specific IFN-γ and IL-10 production in blood from dogs with leishmaniosis at diagnosis and correlate these findings with disease severity, humoral immune response and blood parasitemia." (PMID 27260142, 2016). "Patients with indeterminate Chagas disease produce higher levels of IL-10; IL-10 controls the inflammatory immune response generated by the parasitic infection and prevents damage to the myocardium." (PMID 27115869, 2016). "Additional findings showing reduced IL-10 levels in coinfected children in the context of lower parasitemia are consistent with previous studies showing that the level of parasitemia closely reflects the IL-10 pattern." (PMID 27418744, 2016). "Pathogen-specific effector CD4 T cells are the major source of IL-10 following prolonged viral and parasitic infection." (PMID 27732671, 2016). "Here, we identify a novel pathway of IL-10-dependent control of tissue pathology during parasitic infection." (PMID 26765224, 2016). "Here, we identify a novel pathway of TNF regulation by IL-10 from Tr1 cells during parasitic infection." (PMID 26765224, 2016). "Further, the heterogeneity of study designs and methodologies utilized for IL-10 measurement prevents the generation of conclusive evidence either for or against the role of this cytokine in parasitic infection tolerance." (PMID 25888883, 2015). "The immunological role of anti-inflammatory cytokine, Interleukin 10 (IL10), has been well-documented in parasite infections and considered as a key regulatory cytokine for VL." (PMID 25941808, 2015). "There was a strong positive relationship between blood stream parasitemia and IL-6 (Spearman rho 0.677, P< 0.0001) as well as IL-10 (Spearman rho 0.599, P< 0.0001)." (PMID 26090964, 2015). "In this study, we reveal the mobilization of IL-10-expressing Ly6C- monocytes and macrophages after the control of the first peak of parasitemia when a M2-type regulatory immune response arises in the liver of T. congolense—infected mice." (PMID 26020782, 2015). "An independent role for IL-10 stimulating hepcidin secretion during patent parasitemia is supported by our experimental observations that IL-10 induces hepcidin in a dose-dependent manner through STAT3 phosphorylation." (PMID 24520384, 2014). "These IL-10-secreting B cells are characteristic of functional Bregs, which are activated during parasite infection and are thought to play an important role in controlling inflammation and pathology associated with S. mansoni infection." (PMID 24466007, 2014). "Similar to a previous report, mice conditionally for IL-10 production by CD4 T cells had a trend for lower parasitemia during co-infection." (PMID 24787713, 2014). "The results from many studies have clearly identified IL-4/IL-5/IL-10 as important regulatory cytokines in parasitic infections, such as infection by Schistosoma mansoni in mice and humans, Schistosoma haematobium, Trichuris muris, and Trichinella spiralis." (PMID 24637903, 2014). "We have recently provided evidence from a clinical study that parasitemia, interleukin-10 (IL-10) and interleukin-6 (IL-6) concentration were significantly associated with plasma hepcidin concentration in Kenyan children with acute falciparum malaria." (PMID 24520384, 2014).
parasitemia (continued). "IL-10 levels measured concurrently in plasma were significantly higher among children with parasitemia at the time of the blood draw compared with children with no parasitemia (median 30.4 pg/ml vs 11.4 pg/ml, P = 0.0035), consistent with prior reports." (PMID 24415936, 2014). "Correlation analysis demonstrates that despite the absence of correlation between IL-6 and parasitemia, a correlation between IL-10 and parasitemia levels was observed." (PMID 24741587, 2014). "It is possible that the higher IL-10 levels at convalescence were reflecting a response to submicroscopic parasitemia from uncleared/recrudescent or new infections." (PMID 23437061, 2013). "Although several different cell populations have been established as sources of IL-10 after parasite infection, secretion of this cytokine from B cells is important in the development of susceptibility to parasite infection." (PMID 23071588, 2012). "Finally, B cell-deficient μMT mice developed significantly lower levels of parasitemia after B. microti infection and exhibited lower levels of serum IL-10 compared to wild-type mice, suggesting that IL-10-producing B cells may play a role in susceptibility to infection with B. microti." (PMID 23071588, 2012). "Once parasitemia is under control, regulatory cytokines such as IL-10 and transforming growth factor (TGF)-β are required to reduce the risk of severe disease." (PMID 22973442, 2012). "For example, the positive correlation between IL-10 levels and P. vivax density and the detection of low plasma concentrations of IL-10 in asymptomatic carriers of very low parasitemias allow for two competing interpretations." (PMID 22973442, 2012). "While parasitemia was not enhanced in recipients given CD19+ B cells isolated from naïve mice, the transfer of IL-10-producing B cells isolated from infected mice induced greater parasitemia in recipient mice." (PMID 23071588, 2012). "The functional polarization of macrophages into IL-10 producers characterized as M2 cells has been long understood to play a crucial role in the success of parasite infection process." (PMID 22292094, 2012). "Following parasite infection, IL-10 production by Bregs is important for maintaining peripheral tolerance by inhibiting B and T cell-mediated immune responses and inflammation necessary for efficient pathogen clearance." (PMID 23071588, 2012). "Interleukin-10 (IL-10) is an anti-inflammatory cytokine and thus increased production during parasite infection was necessary to ameliorate the disease outcome." (PMID 21439091, 2011). "These IL-10-producing Th1 cells are the major source of IL-10 in mice suffering from chronic intracellular parasite infection." (PMID 22216188, 2011). "Inosine, a purine nucleoside, proved to be the most effective agent at improving peripheral blood parasitemia from a group of agents tested, including TGFβ1, dexamethasone, and IL-10." (PMID 21483851, 2011). "Future studies should measure antenatal levels of IL-10, and assess its relationship to parasitemia and pregnancy outcomes, and its utility for monitoring interventional trials." (PMID 18230163, 2008). "Future studies should measure IL-10 levels throughout gestation to assess relationships to antenatal parasitemia and to pregnancy outcomes." (PMID 18230163, 2008). "However, IL-10 secretion begins late in viral, bacterial, fungal, and parasitic infections, when the PAMPs, DAMPs, and native Ag amounts are greatly reduced." (PMID 40283387, 2025). "In parasitic diseases such as leishmaniasis, there is a complex interaction between different Leishmania species and the host immune system, mediated by cytokines such as IL-1β and IL-10, which determines the clinical outcomes of the disease." (PMID 41200163, 2025). "At 30 and 60 dpi, however, IL-10 expression was significantly higher in CL Brener-infected animals (p < 0.05), indicative of a delayed compensatory immune regulation in response to persistent inflammation and parasitemia." (PMID 41394106, 2025).